IFNL3 (interferon lambda 3)
Diseases named in the same sentence as IFNL3 in open-access papers (continued):
Sharing a sentence is not in itself a finding about the gene and the disease.
infection (112 papers, 2010 to 2025). The state of being infected such as from the introduction of a foreign agent such as serum, vaccine, antigenic substance or organism. "It is therefore possible that changes in the cell structure of the lung results in decreased secreted IFNL3 which causes an impaired immune response to infection." (PMID 29562888, 2018). "In addition, the predominance of IFNL3-gene C or T-allele in CHCV infection reveals one of the following situations: d." (PMID 37928048, 2023). "Genes encoding interferons (Ifnb, Ifnl2 and Ifnl3), chemokines (Ccl7, Ccl5, and Cxcl10), and ISGs (Ifit1, Ifit2, Ifit3b, Oas3, Ifi44, Rsad2, and Isg15, among others) were prominently represented among those induced by infection in Ifnar1-/- mice." (PMID 34591933, 2021). "Therefore, the association of the IFNL3 SNPs with certain biochemical parameters and their impact on treatment-induced clearance of infection might be of interest, independent from treatment strategies." (PMID 24204859, 2013). "In PMH, quantification of Ifnb1, Ifnl2, and Ifnl3 transcript levels [murine Ifnl1 is a pseudogene] showed that infection elicited the expression of only Ifnb1, which was 40 times higher at 24 h than at 72 h p.i.." (PMID 34858876, 2021). "IFN-λ genes (IFNL1, IFNL2, IFNL3) were the most highly expressed among the interferon genes at both 12 and 24 h post-infection for all viruses." (PMID 32849329, 2020). "Laser capture microdissection was utilized to compare infected and infection adjacent cells, and was further stratified by IFNL3 rs12979860 genotype." (PMID 26313459, 2015). "Interestingly, ERB-derived lung organoids undergo significant upregulation of both the IFN1-like and IFNL3 genes at 3 days post-infection with MARV, as well as in response to SeV, H1N1 influenza virus and VSV infections." (PMID 41181097, 2025). "The rs8099917 T allele, from the IFNL3 gene, showed a higher frequency inboth groups; however, it was not possible to establish an association withHDV infection [OR = 1.42 (0.42 - 4.75; p = 0.556 (95% CI)." (PMID 38221914, 2024). "Lambda interferons (IFNLs) include IFNL1/interleukin-29 (IL-29), IFNL2/IL‐28A, IFNL3/IL‐28B, and IFNL4, all of which are critical for a balanced antiviral response in the respiratory tract for optimal protection against infection and minimizing associated damage." (PMID 38703289, 2024). "The influence of IFNL3/4 SNPs and IL-28RA genotypic background on macrophage polarization and function remains to be studied, but affecting macrophages in general will have a significant impact on host responses to infection." (PMID 26038748, 2014). "IFNB1 expression was also elevated following infection; however, IFNL1, IFNL2, and IFNL3 expression clearly dominated the innate immune response." (PMID 36268025, 2022). "At 24 and 48 h post-infection, the predominant interferons induced in the primary airway cells at the mRNA level were IFNβ, IFNL1, and IFNL2/IFNL3 (qRT-PCR cannot distinguish these isoforms), with IFNL1 and IFNL2/3 being the most upregulated." (PMID 34899695, 2021). "Consistent with the findings in HT-29 cells, we found that following infection with RV or vesicular stomatitis virus (VSV), an excellent source of RNA PAMPs, human IECs expressed much more (50 fold) IFNL3 than IFNB." (PMID 30460894, 2018). "The differences in ISG expression were not dependent on changes in IFN gene expression, as Ifnl3, Ifnb1, and Ifna12 were not vastly altered throughout the course of infection (days 1, 2, 3, or 5 p.i.)between WT and Ifnlr1–/– mice." (PMID 38973611, 2024). "They observed that after infection withSARS-CoV-2, endothelialcells from infected lung-on-chips showed significant upregulationof TNF-α, IL6, and IFN-β and more modest increase ininterferon-λ1 (IFNL1) and IFNL3 expression." (PMID 38559954, 2024).
infection (continued). "We further investigated the possible differences in host defense pathways by RNA-seq analysis and found an increase in some key host defense transcripts, such as IFNL1, IFNL3, CXCL10, and CXCL11, in response to infection with recent EV-D68 isolates compared to Fermon." (PMID 37376591, 2023). "In both NTC and MDA5-/- cells, ΔHA infection upregulates IFNB and IFNL3." (PMID 32790753, 2020). "We observed increased IFNB1, IL29/IFNL1, IL28A/IFNL2, IFNL3, RSAD2, and CXCL10 post infection." (PMID 33409274, 2020). "The IFNL3/IFNL4 studies featured here were broadly not able to adjust for this duration of infection." (PMID 29397014, 2018). "This includes most Ifna isoforms, Ifnl2, Ifnl3, Ifnb1, Tnf, and numerous other chemokines and cytokines representing the acute pDC anti-viral response that is absent in suppressed pDCs at later stages of infection." (PMID 39920132, 2025). "Interestingly, SNPs in the IFNL3 locus have been shown to affect the expression of IFNL3 not only in liver which is the site of infection but in PBMCs and whole blood with the minor (unfavorable) allele resulting in less IFNL3 expression." (PMID 25705565, 2014). "Upon in vitro infection with ZIKVBR, a marked induction of mRNA expression of IFNB1, IFNL1, IFNL2 and IFNL3 genes but not of IFNE was observed." (PMID 32745093, 2020). "It is not clear what function IFNL3 serves in the context of SARS-CoV-2 infection but the sustained levels of IFNL3 across all disease severity groups suggest that it is worth investigating a potential role in long-COVID which can impact patients, regardless of severity of initial infection." (PMID 38953458, 2024).
tumor (12 papers, 2013 to 2025). "The results showed that endogenous IFN-λ expression may be mainly caused by copy number amplification of IFNL2 and IFNL3 genes in tumor patients." (PMID 37697300, 2023). "Overall, our analysis showed that IFN-λ cancer-specific expression may be caused by copy number amplification of IFNL2 and IFNL3 in tumor patients, and most IFN-λ related genes also had copy number amplification and expression upregulation in BSE group." (PMID 37697300, 2023). "Moreover, IFN-λ specific expression may be caused by copy number amplification of IFNL2 and IFNL3 in tumor patients and driven cancer progression." (PMID 37697300, 2023). "Specifically, the human genes IFNL2 (which encodes IFN-λ2) and IFNL3 (which encodes IFN-λ3) serve as independent prognostic markers, and their expression can influence tumor progression through the JAK-STAT signaling pathway." (PMID 41294689, 2025). "The significantly regulated genes identified in both KYSE150 and KYSE410 cells were found to be involved in cell adhesion (PCDH family genes, CLDN1, CNTN1), cell apoptosis (MAPK10/JNK3, PYCARD), tumor suppression (TUSC3, SAMD9L) and immunity regulation (IFNL3)." (PMID 32089740, 2020).
cancer (7 papers, 2015 to 2022). A tumor composed of atypical neoplastic, often pleomorphic cells that invade other tissues. "The other possible explanation was that TDF as a nucleotide analogue might have an additional pharmacological effect by inducing a rise in the serum levels of interferon-lambda 3, a potent antitumor activity in murine models of cancer including HCC34,35." (PMID 33446835, 2021).
infectious disease (2 papers, 2017 to 2021). A disorder directly resulting from the presence and activity of a microbial, viral, or parasitic agent in humans. "Single-nucleotide polymorphisms (SNPs) within the IFNL3/IFNL4 gene locus and impact on infectious diseases." (PMID 28293236, 2017). "In mice, commonly used as a model organism for infectious disease and immune function, only IFNL2 and IFNL3 are functional, as IFNL1 and IFNL4 are present as inactive pseudogenes." (PMID 28293236, 2017).
IFNL3 also shares sentences with these, for which no sentence is quoted: chronic hepatitis (9 papers); anemia (8); diabetes (8); Hepatitis B Infection (7); influenza (7); Myelopathy (4); Thrombocytopenia (4); chronic viral hepatitis (3); End Stage Liver Disease (3); HCMV infection (3); pulmonary fibrosis (3); tropical spastic paraparesis (3); cryoglobulinemia (2); diabetes mellitus type 2 (2); herpes labialis (2); Hypertension (2); Lupus (2); lymphoma (2); lymphoproliferative disorder (2); non-Hodgkin lymphoma (2); Acute hepatitis (1); alcoholic hepatitis (1); allergic asthma (1); allergic rhinitis (1); autoimmune disorders (1); brain diseases (1); bronchiolitis (1); cardiovascular diseases (1); cervical cancer (1); chronic periodontitis (1).
A further 49 diseases each share a sentence with IFNL3 in 1 paper.